IL1B (interleukin 1 beta)
Diseases named in the same sentence as IL1B in open-access papers (continued):
Sharing a sentence is not in itself a finding about the gene and the disease.
neuropathic pain (continued). "Microglial MAP kinases can be activated by IL-1β and TNF-α, inducing, via transcription factors such as NFκB, additional production of IL-1β, TNF-α, IL-6, IL-10, TGF-β, PGE2, BDNF, and cathepsin S and promoting the deleterious effects of microglial infiltration and phagocytosis in neuropathic pain." (PMID 24642655, 2014). "The present study demonstrates that intrathecal tramadol and propentofylline depress SNL-induced spinal dorsal horn IL-1β production, which contributes to the synergistic effects of tramadol and propentofylline coadministration on the development of SNL-induced neuropathic pain." (PMID 24009718, 2013).
non-small cell lung carcinoma (45 papers, 2006 to 2026). A group of at least three distinct histological types of lung cancer, including non-small cell squamous cell carcinoma, adenocarcinoma, and large cell carcinoma. "IL1β has been implicated in docetaxel resistance by regulating the development of polyploid large cancer cells in non-small cell lung cancer." (PMID 39766172, 2024). "Elevated expression of interleukin 1 beta (IL1B) mRNA increases the risk of non-small cell lung cancer." (PMID 23155391, 2012). "High IL-1β levels are associated with shorter overall and progression-free survival for non-small cell lung cancer (NSCLC) patients treated with platinum-based combination chemotherapy or with chemotherapy/bortezomib and for pancreatic cancer patients treated with gemcitabine." (PMID 32635472, 2020). "Emerging preclinical evidence challenges the long-standing assumption that Interleukin-1β (IL-1β) uniformly promotes non-small cell lung cancer (NSCLC)." (PMID 41694383, 2026). "Reports indicated IL-1β inhibitors can be used in combinatorial treatments to improve the therapeutic efficacy in patients harboring non-small cell lung cancer at the early stage." (PMID 41145465, 2025). "For example, IL-1β was found to mediate the resistance of non-small cell lung cancer cells to docetaxel by regulating the formation of polyploid giant cancer cells, while its inhibition increased docetaxel sensitivity." (PMID 40299479, 2025). "Meanwhile, IL-1β inhibition significantly reduced the incidence and mortality of non-small-cell lung cancer (NSCLC) in the CANTOS study population." (PMID 39684895, 2024). "The NLRP3 inflammasome was found to be activated in non-small-cell lung cancer, promoting the release of IL-1β and IL-18." (PMID 39201564, 2024). "The results showed that α-viniferin and ε-viniferin significantly inhibited EMT, invasion and migration in TGF-β1- or IL-1β-induced non-small cell lung cancer." (PMID 35684095, 2022). "Interleukin-1 beta (IL-1β), a proinflammatory cytokine, correlates with tumor progression in non-small cell lung cancer (NSCLC) patients in multiple studies." (PMID 31941995, 2020). "In addition, research has shown that chronic IL-1β-induced inflammation regulates EMT memory phenotypes via epigenetic modifications in non-small cell lung cancer." (PMID 40593461, 2025). "Notably, combining IL-1β inhibition with PD-1 blockade has shown a synergistic effect in a non-small cell lung cancer (NSCLC) mouse model, significantly suppressing tumor progression." (PMID 40109347, 2025). "IL-1β may also act synergistically with IFN-γ to promote maximal upregulation of PD-L1 in non-small cell lung cancer cells through activation of MAPK signaling thereby producing immunosuppressive effects." (PMID 38762529, 2024). "Wang and coworkers found that IL-1β is abundant in non-small-cell lung cancer (NSCLC) patients." (PMID 34926688, 2021). "Furthermore, IL-1β protein is significantly increased in the plasma of advanced non-small-cell lung carcinoma (NSCLC) patients treated with Bortezomib (trial protocol: NCT01633645)." (PMID 30142927, 2018). "In lung cancer, particularly in Non-Small Cell Lung Cancer (NSCLC), TAMs in the TME play an important role because they are associated with the production of various pro-inflammatory cytokines and chemokines (IL-1β, IL-6, IL-8, IL-12, and IL-18), promoting tumor growth and metastasis." (PMID 41560727, 2025). "Our recent work has revealed that pollution activated macrophages can drive non-small cell lung cancer initiation in an EGFR mutant mouse model, primarily via the pro-inflammatory cytokine IL1β (Research Square 10.21203/rs.3.rs-1770054/v1)." (PMID 36930945, 2023). "In such studies, survivors of childhood ALL exhibiting poor sleep were found to have elevated plasma levels of IL-6, IL1b and CRP, and elevated IL-6 levels were correlated to poor sleep in non-small cell lung cancer patients receiving chemoradiotherapy." (PMID 36213755, 2022).
non-small cell lung carcinoma (continued). "In particular, IL-1B, IL6, and IL8 genes are downregulated upon promoter methylation in Non-Small-Cell Lung Cancer (NSCLC), whereas IL23, a member of IL6 family, is epigenetically regulated by both histone acetylation and DNA methylation." (PMID 31366176, 2019). "Here, we aimed to test whether tumor-derived small EVs (TEVs) isolated from sensitive and osimertinib-resistant (OR) non-small-cell lung cancer (NSCLC) cells may promote EMT via fibronectin binding to α5β1 integrin as well as suppress the immune system and if these effects may be favored by IL-1β." (PMID 40725070, 2025). "Many articles have shown that IL1B SNPs may be involved in the pathogenesis of NSCLC and thyroid cancer in Chinese population and can also be used as a new prognostic genetic biomarker for non-small cell lung cancer." (PMID 33240582, 2020). "A recent work using mouse models of non-small cell lung cancer (NSCLC) and triple-negative breast cancer (TNBC) showed that IL-1β secretion by myeloid cells was independent of inflammasome activation and gasdermin D pore formation." (PMID 35517498, 2022).
aneurysm (44 papers, 2009 to 2025). Bulging or ballooning in an area of an artery secondary to arterial wall weakening. "The serum IL-1β, IL-1RA, and IL-1RA/IL-1β ratio were associated with the inflammation-related proteins in aneurysm tissues." (PMID 36466848, 2022). "In contrast, one study that tested the effect of IL-1β deficiency in the calcium chloride model reported significantly larger AAA size six weeks after aneurysm induction compared to controls." (PMID 36289670, 2022). "They proposed that necrotic VSMCs in aneurysms can release IL-1β, inducing IL-6 production, thereby promoting vascular inflammation and accelerating aneurysm progression." (PMID 40244203, 2025). "Both IL-1β and TNF-α have been associated with the progressive inflammatory process that promotes aneurysm progression." (PMID 40440080, 2025). "The expression of proinflammatory cytokines, such as IL-1β and IL-6, was elevated in the aneurysm and circulating system of mice with AAA, which was restrained after ATL-I treatment." (PMID 39958337, 2025). "Animal models of IAs and abdominal aortic aneurysms (AAAs) suggest that IL-1β upregulation promotes aneurysm progression by regulating collagen biosynthesis in the aneurysm wall." (PMID 40244203, 2025). "In animal models of aneurysms and aortic dissections, disease induction led to elevated IL-1β tissue levels, and concurrently, breakage and reduction in elastic fiber content." (PMID 39232217, 2024). "The increased expression of IL-1β in mult-AA compared to sing-AAA indicates inflammatory processes play a role in aneurysm formation in patients with multiple arterial aneurysms." (PMID 37238981, 2023). "Third, the inflammasome is the primary regulator of mature IL-1β production, and IL-1β has well-documented contributions to aneurysm progression." (PMID 41541085, 2023). "A significant attenuation of pro-inflammatory cytokines, including IL-1β and HMGB1, associated with aneurysm formation were seen in the SPL-treated mice compared to saline-treated mice." (PMID 36776267, 2023). "To better understand how the absence of Crp3 prevents AAA development, we treated SMCs with IL-1β, one of the main cytokines found at aneurysm lesions." (PMID 38173933, 2023). "They found that the IL-1.ra to IL-1β ratio was highly accurate in assessing aneurysm rupture (C statistic =0.91) and provided a better discriminability for symptomatic aneurysms when combined with the PHASES score than using the PHASES score alone." (PMID 37928138, 2023). "They demonstrated that aneurysm wall enhancement was associated with pyroptosis in UIA tissues and pyroptosis-related serum cytokines such as the inflammatory cytokine IL-1β and anti-inflammatory cytokine IL-1 receptor antagonist (IL-1.ra)." (PMID 37928138, 2023). "A significant attenuation of inflammatory cytokines, including IL-1β and HMGB1, associated with aneurysm formation was seen in the PBN-treated mice compared with Ang II alone." (PMID 35315432, 2022). "The serum IL-1β and IL-1.ra were correlated with the pyroptosis-related proteins in aneurysm tissues." (PMID 35155635, 2022). "Previous research revealed an increase ininfiltrated macrophages exhibiting a robust production of cytokines, including IL-6, IL-8, TNFα, and IL-1β, and specific patterns of macrophage polarization involving in aortic inflammation and aneurysm formation." (PMID 33158139, 2020). "Another potent inflammatory cytokine, IL-1β, has been shown to be involved in the vascular inflammation and aneurysm formation in a murine model of LCWE-induced vasculitis." (PMID 29765083, 2018). "In a study using pre- to post-operative arterial blood samples for 13 days in patients with ruptured aneurysms and intact aneurysms, an increase of TNFα, IL-1β, and IL-6, was found." (PMID 29483877, 2018). "In our current and earlier studies, the increase in IL-1β and TNF-α and the imbalance between MMP-9 and TIMP-2 were associated with aneurysm rupture in ovariectomized aneurysm rats." (PMID 28969701, 2017).
aneurysm (continued). "In fact, IL-1β is thought to be a key inflammatory mediator in cerebral aneurysm as disruption of the IL-1 gene decreased the incidence of mature aneurysms in a mouse model." (PMID 23316103, 2012). "This suggests that the ratio of IL-1β to IL-1ra might serve as a potential biomarker for predicting aneurysm rupture or growth." (PMID 40244203, 2025). "This study showed a decrease in aneurysm progression, suggesting that IL-1β could be a potential target for treating thoracic aortic aneurysms." (PMID 40002744, 2025). "We hypothesized that NLRP3 inhibition via MCC950 would protect against aneurysm rupture, decrease the M1/M2 macrophage ratio, and reduce the IL-1β expression in the vessel walls." (PMID 41541085, 2023). "Taken together, higher MLDGS score may represent higher expression of IL1B, TLR4, VEGFA and MMP2, and lower expression of NOS3, implying inferior vascular stability at the molecular level and high risk of aneurysm rupture and CVS onset." (PMID 36844725, 2023). "This trial showed similar aneurysm growth in both treatment and control groups, but was undoubtedly underpowered to test any conceivable effect and therefore the effect of IL-1β neutralization on AAA growth remains unclear." (PMID 36289670, 2022). "The pyroptosis-related proteins, e.g., IL-1β, IL-1.ra and IL-1.ra/beta ratio, may serve as a potential biomarker to predict the aneurysm rupture or growth." (PMID 35155635, 2022). "Interestingly, among the four sCAEBV patients with elevated IL-1β, three had clinically diagnosed angiopathy, one had intracranial vascular lesion with multiple cerebral bleedings, and two had aneurysms." (PMID 35464987, 2022). "It is noteworthy that IL-1β deficiency created by gene knockout attenuated aneurysm development in the elastase perfusion but not the calcium chloride model." (PMID 36289670, 2022). "Again, inhibition of Il-1β by Il-1 receptor antagonist (Il-1Ra) or an anti-Il-1β antibody significantly suppressed aneurysm formation after AngII infusion, indicating that Il-1β might be a promising target for TAA and AAA treatment." (PMID 34572082, 2021). "Similarly, in WT animals, an amplified expression of proinflammatory cytokines IL-1β and IL-6 was visible within the lesions upon aneurysm development." (PMID 33467682, 2021). "To determine if pyroptosis plays a role in human and mouse aneurysms, we evaluated markers of pyroptosis including NLRP3, CASP1, GSDMD and IL‐1β, and also analysed MMP2/9 in human aortic aneurysms and mouse AAA." (PMID 39601144, 2024). "The mRNA expression of the downstream NLRP3 pathway components caspase-1, IL-1β, and GSDMD is also increased in the aneurysm tissue compared to healthy vessels." (PMID 41541085, 2023). "Further, aneurysm tissue also demonstrated higher mRNA expression levels of the NLRP3 pathway components caspase-1, IL-1β, and GSDMD." (PMID 41541085, 2023). "Our finding that naringenin or TFEB inhibited NLRP3 inflammasome activation and reduced IL-1β secretion during AAA is consistent with previous reports that depletion of the NLRP3, caspase-1, and IL-1β inflammasomes protect against aneurysm formation in mice." (PMID 35228523, 2022). "In their study, the interleukin-1beta (IL-1β), matrix metalloproteinase-2 and matrix metalloproteinase-9 (MMP-2, MMP-9), and nitric oxide synthetase (NOS) in aneurysm wall were all decreased compared to normal artery." (PMID 34847937, 2021). "The resultant aneurysm out-pouching is likely accompanied by local increase in chemokines and cytokines (IL-1β, IL-17, TNF-α) in blood of the aneurysm lumen." (PMID 34203780, 2021). "In the wall of an AAA there is up-regulation of pro-inflammatory IL-1β, IL-6, IL-10 and TNF-α, which have been shown to positively correlate with aneurysm growth." (PMID 20964810, 2010). "Notably, the levels of serum IL-1β and IL-1.ra were correlated with the relative levels of GSDMD, MMP2 and CD68 in aneurysm tissues." (PMID 35155635, 2022).
aneurysm (continued). "For the AngII No AAA cohort, staining intensity and abundance of IL-1β were low except for the tissue with an apparent aneurysm where all the positive staining resided." (PMID 31069328, 2018). "Three hub genes, NLRP3, IL1B and IL18, were identified using Cytoscape software and the WGCNA correlation module, and external validation revealed statistically significant differences between the expression of these hub genes in the ruptured and unruptured aneurysm groups (p < 0.05)." (PMID 37752552, 2023). "Therefore, downstream activation of critical pro-inflammation factors like IL1B and IL18 in pyroptosis process, might also play a role in aneurysm progression." (PMID 34895131, 2021). "Considering the high amount of inflammatory cells infiltrating the aneurysm wall, the first condition consisted of the interaction with activated immune cells, whereas the second one was based on the exposure to a combination of recombinant inflammatory cytokines TNF-α/IL-1β at 25 ng/ml each." (PMID 28446225, 2017).
autoinflammatory syndrome (44 papers, 2010 to 2026). A group of disorders of the innate immune system characterized by attacks of seemingly unprovoked inflammation without significant levels of either autoantibodies or autoreactive T cells more characteristic of autoimmune disease. "For example, autoinflammatory syndromes with gain-of-function mutations in NLRP3 are mainly driven by myeloid-production of IL-1β, while syndromes due to gain-of-function mutations in NLRC4 are associated with epithelial-production of IL-18." (PMID 39468985, 2024). "IL-1β, IL-18, and IL-33 were within normal limits or undetectable, and no mutations were found in genes related to the pathogenesis of autoinflammatory syndromes (MEFV, MVK, TNFRSF1A, NLRP3, and NLRP12)." (PMID 34829952, 2021). "FMF is an auto-inflammatory syndrome associated with the activation of phagocytic cells and an over-secretion of IL-1β." (PMID 30828327, 2019). "Increased IL-1β secretion is a hallmark of genetic auto-inflammatory syndromes associated with the activation of the inflammasome, predominantly in the cells of innate immunity." (PMID 30079049, 2018). "NLRP3 gain‐function mutation has been shown to cause Muckle–Wells syndrome (MWS), which is an autoinflammatory syndrome characterized by an excessive secretion of IL‐1β." (PMID 29531021, 2018). "Interestingly, patients suffering from NLRP1-associated autoinflammatory syndrome (also characterized by high IL-18 and IL-1β levels) had higher peripheral blood transitional B cells, bearing the regulatory phenotype CD24highCD38highCD27low/neg." (PMID 38392193, 2024). "Mutated NLRP3 causes autoinflammatory syndromes resulting in excess IL-1β production." (PMID 31319552, 2019). "Specifically, TNF-α induces the production of IL-1β and IL-6, with the former being a crucial mediator of the inflammatory response, causing various autoinflammatory syndromes, and the latter being secreted by T cells and macrophages to stimulate the immune response." (PMID 27382402, 2016). "Familial autoinflammatory syndromes, such as Muckle-Wells-Syndrome, are linked to excessive secretion of IL-1β and have helped to elucidate the mechanisms that regulate the secretion of active IL-1β." (PMID 22768094, 2012). "Elevated IL-1β expression can produce numerous autoinflammatory syndromes and exacerbate injury during chronic diseases and acute tissue injury." (PMID 38535466, 2024). "As an essential factor for inflammatory response, IL-1β is closely bound up with cellular functions, such as cell multiplication, differentiation, and apoptosis, which contribute to many different autoinflammatory syndromes." (PMID 37854095, 2023). "Elevated levels of IL-1β, IL17-A, and PAI-1 have been associated with various autoinflammatory syndromes and diseases." (PMID 37659022, 2023). "It is well known that patients with dysregulated cytokine production of IL-1β as seen in autoinflammatory syndromes are known to exhibit neuropsychiatric symptoms." (PMID 35538558, 2022). "To date, there are limited data on the role of IL‐38 in IL‐1β or NLRP3 related auto‐inflammatory syndromes." (PMID 33620105, 2021). "We thus decided to subject them to a trial of drugs used in autoinflammatory syndromes, such as colchicine or the anti-IL1-β monoclonal antibody canakinumab, with lasting benefit." (PMID 34829952, 2021). "Canakinumab, a human monoclonal anti-IL-1β antibody, is indicated for the treatment of different autoinflammatory syndromes in adults, adolescents, and children and it has recently been approved for AOSD treatment." (PMID 30298010, 2018). "Inflammasomes were activated in auto-inflammatory syndrome patients, who also exhibited conversion of pro-IL-1β to an active form to secret by caspase 1 activity." (PMID 30361689, 2018). "Ferritin is increased at levels often exceeding 4000 ng/ml in autoinflammatory syndromes like Still’s disease and acute gouty arthritis that are mediated through excess production of IL-1β and IL-18." (PMID 28918754, 2017).